IFIT5 (interferon induced protein with tetratricopeptide repeats 5)
Diseases named in the same sentence as IFIT5 in open-access papers (continued):
Sharing a sentence is not in itself a finding about the gene and the disease.
glioblastoma (1 paper, 2018). The most malignant astrocytic tumor (WHO grade IV). "It is important to investigate in better details the involvement of IFIT5 in glioblastoma development and if it exists an association with survival/aggressiveness." (PMID 29844869, 2018).
ischemic cardiomyopathy (1 paper, 2021). Ischemic cardiomyopathy is a cardiomyopathy in which a weakness in the muscle of the heart due to inadequate oxygen delivery to the myocardium with coronary artery disease being the most common cause. "IFIT3 may be a potential therapeutic target for ischemic cardiomyopathy, and IFIT1 and IFIT5 are key genes that are used to predict treatment response in patients with microvascular disease in the early stage." (PMID 34753383, 2021).
liver cancer (1 paper, 2023). An epithelial or non-epithelial malignant neoplasm that arises from the liver. "Among the genes associated with the prognosis of liver cancer, the genes associated with shorter survival period are AGO2, DCPS, IFIT5, LARP1, NCBP2, NUDT10, and NUDT16; the genes associated with longevity are EIF4E3, EIF4G3, METTL1, NCBP1, NSUN2, NUDT11, NUDT4, and WDR4." (PMID 36845384, 2023).
pancreatic cancer (1 paper, 2015). "In addition, IFIT1 was detectable in normal pancreas and in 9 out of 11 cancer samples, while IFIT2 and IFIT5 could not be found in either normal pancreas or pancreatic cancer samples." (PMID 25650658, 2015).
parasitic disease (1 paper, 2017). "Over both species, the strongest biomarkers for discrimination between viral and bacterial/parasitic disease were UBL1 (PXMP2), IFIT5, GAL3, NFX, VHSVIP4 (VIG4), DEXH (DDX58), unknown CA054694 MX1 RSAD, IFI44A, and HERC6." (PMID 28702195, 2017).
reovirus infections (1 paper, 2020). "We further analyzed the proteomic data of in vivo reovirus infections and, interestingly, found that classical reovirus and NDRV infections significantly upregulated the expression of RIG-I, MDA5, IRF3, and several ISGs, such as Mx, viperin, IFIT5, and IFITM2 in both the liver and spleen." (PMID 33344524, 2020).
infection (45 papers, 2013 to 2025). The state of being infected such as from the introduction of a foreign agent such as serum, vaccine, antigenic substance or organism. "When both human and chicken IFIT5 were overexpressed in chicken cells, they were found to inhibit viral replication and likewise, when chicken IFIT5 was knocked out from these cells, they were much more susceptible to infection." (PMID 32477965, 2020). "In duck, for example, induced expression of antiviral gene IFIT5 was observed only following infection with low pathogenic virus, whereas highly pathogenic H5N1 virus strain did not induce expression of this gene." (PMID 29475453, 2018). "Among others, 2’-5’ oligoadenylate synthetase-like (OASL), Interferon induced protein with tetratricopeptide repeats 2, 3 and 5 (IFIT2, IFIT3, IFIT5) were up-regulated in female-derived macrophages upon infection." (PMID 40794782, 2025). "The expression of IFIT5 varies among ducks with different levels of viral resistance during infection." (PMID 39518785, 2024). "Duck IFIT5 is highly homologous to chicken IFIT5, duck IFIT5 expression increases rapidly after infection with duck hepatitis A virus type 3 (DHAV-3), suggesting that IFIT5 plays a role in the immune response to DHAV-3 infection." (PMID 39518785, 2024). "We found that ALV-J infection significantly increased the proportion of CD8+T cells in chickens and up-regulated the expression of cytotoxic genes like Granzyme A and antiviral genes like IFIT5 at 14 days post-infection (dpi)." (PMID 39696681, 2024). "IFIT1 and IFIT5 possess the capability to detect uncapped viral triphosphate-RNA, which is an additional indicator of infection." (PMID 39303913, 2024). "Before infection, the cis-element was linked to IFIT1B and IFIT5, which were dynamically reshuffled to link with IFIT1, IFIT2, and IFIT3 after infection." (PMID 36195603, 2022). "The results showed that more autophagosomes were observed in HP-PRRSV-infected MVECs, and the expression of IFN-α, IFIT3, and IFIT5 decreased or increased at different time points after infection." (PMID 36146725, 2022). "We overexpressed or knocked down IFIT5 in DF-1 cells and infected them with ARV to analyze the effect of IFIT5 on the expression of innate immune signaling pathway–related factors during ARV infection by real-time quantitative PCR." (PMID 36187980, 2022). "Other IFN-induced effector proteins with tetratricopeptide repeats (IFIT1-3, IFIT5) were 1.6–3.5-fold induced after infection and function in RNA degradation and inhibition of translation." (PMID 34777295, 2021). "To confirm these results, we used real-time quantitative PCR (qPCR) to analyse mRNA levels of the “classical ISGs” Mx1, IFI6 and IFIT5 upon infection with the knockout viruses." (PMID 33352813, 2020). "IFIT5 was overexpressed in CEF cells infected with H5 viruses at 12 h post infection and downregulated in the Ross [2x] group." (PMID 32381003, 2020). "In the present study, the upregulated expression of IFIT5 was induced following DTMUV infection in DEFs; however, its role in the antiviral process and immune regulation requires further study." (PMID 30809531, 2019). "Infection of this fibroblast IFIT5-ko cell line with RNA viruses such as Newcastle disease virus and VSV substantially supported viral replication in both cases." (PMID 31040842, 2019). "A slight reduction in IFIT5 expression was observed at 8 hours post-infection (hpi) was reconstituted at 24 hpi." (PMID 29717152, 2018). "In the present study, we detected up-regulation of IFIT5 following DTMUV infection in the ovarian follicles, however, its role in antiviral process and immune regulation requires further investigation." (PMID 27066001, 2016). "In the IFE cells, infection was associated with the upregulation of interferon regulatory and inducible genes (IRF, IRF9, IFIT5, IFIH1), while a downregulation of IFI35 and IFI6 was observed, potentially indicating a mechanism to prevent excessive immune activation." (PMID 38743760, 2024).
infection (continued). "Following infection of PAMs with ASFV-WT and ASFVΔMGF360–4L, IFIT2, IFIT3, and IFIT5 transcription were significantly up-regulated." (PMID 41153955, 2025). "Genes relating to inflammation, repair, apoptosis and antiviral responses (e.g., IFI27L2, IFIT5, CXCL10-like,) were upregulated in the per-acute phase of infection (1–3 dpi) and continually increased in its transcription to 4–6 dpi." (PMID 40758745, 2025). "In resistant birds, two genes affiliated with the interferon activation pathway were increased upon infection, TNF alpha induced protein 2 (TNFAIP2) and interferon induced protein with tetratricopeptide repeats 5 (IFIT5)." (PMID 37005445, 2023). "It is interesting to note that several of these genes (IFIT5, LY96, RNF213 and EPST1) were previously identified in a study examining LPAI and HPAI infection in ducks and chickens." (PMID 35327988, 2022). "The results showed that compared to the infection control group at three time points, the expression of IFIT3 and IFIT5 was significantly enhanced by the 100 μg/mL APS treatment at the mRNA and protein levels." (PMID 36146725, 2022). "VN1203 infection induces a much more rapid and robust response of IFN inducible genes (such as RSAD2/Viperin and IFIT5) in the duck than BC500 infection does." (PMID 34804075, 2021). "Overexpression of SOCS1 in chIFN-α-stimulated DF-1 led to a relative decrease in expression of interferon-stimulated genes (ISGs; MX1 and IFIT5) and increased viral yield in response to PBG98 infection." (PMID 29235573, 2017). "We identified important genes DE in both our in vitro and in vivo infection models consistent with previous studies, namely, TLR3, IFIH1 (MDA5), SOCS1, OASL, DDX60, STAT1, MX1, CMPK2, LY96 (MD-2), STAT1, STAT2, TRIM25, IRF7, and IFIT5." (PMID 38675946, 2024). "Notably, multiple antiviral proteins were also dramatically decreased in PAMs during the PRRSV-ADE infection, including ISG15, ISG20, IFIT1 (ISG56), IFIT2 (ISG54), IFIT3 (ISG60), IFIT5 (ISG58), OAS1, Mx1, RSAD2, TRIM22, TRIM25 and TRIM34, except for TRIM52." (PMID 36680075, 2022). "This may explain the observation in this study that expression of IRF7 in KO IFNAR1 cells promotes the expression of IFIT5 and IRF1 at the later stage of infection." (PMID 35891486, 2022). "At the transcriptome level, the high expression levels of viral sensors MDA5 (IFIH1), R1G-1 (DDX58), and ISGS (ISG15, Mx1, Mx2, RSAD2, IFIT3, and IFIT5) and transcription factors like IRF-7 and STAT-1 that induce ISG expression were found in lymphocytes during virulent PPRV infection." (PMID 34631844, 2021). "Overexpression of IRF7 in KO IFNAR1 cells infected with DTMUV partially restored the expression of IFN-β at 12–48 hpi, IFIT5 at 36–48 hpi, IRF1 at 48 hpi, and MX1 at 12–48 hpi, indicating a type I IFN-independent role of IRF7 in the induction of these genes during DTMUV infection." (PMID 35891486, 2022). "Notably, the initial temporary upregulation of IFN-α, IFIT3, and IFIT5 in MVECs was observed, which may be attributed to the stress reaction of the innate immune response in MVECs to HP-PRRSV at the early stage of infection." (PMID 36146725, 2022). "Among the expression upregulated ISGs, MX, IFIT5, OAS, VIPERIN, ISG12, and IFI6 had the largest expression levels of upregulation (hundreds-fold), and these ISGs all showed a certain pattern of changes: persistent upregulation in the early stage of infection, peaking 3–5 days after infection." (PMID 33614762, 2021). "Results showing that IFIT1, IFIT2, and IFIT3, but not IFIT5, were induced with similar kinetics by DV infection suggest the possibility of co-regulation, and also the coordination and non-redundant functioning of these molecules in IFN-mediated signaling events, as observed in neurons." (PMID 24223959, 2013).
infection (continued). "Therefore, we hypothesized that IFN might be induced during early infection, as indicated by the subsequent enhanced production of ISGs because increased expression of a variety of ISGs, such as OSAL, MX1, IFIT5, ISG12-2, RSAD2, IFI35, protein kinase R (PKR), and IFI27L2, was found in this study." (PMID 24168272, 2013). "At the earlier time points post-infection, we did not observe any overlap with down-regulated mRNAs; however, 27 up-regulated mRNAs were common to all early treatment groups, including TLR3, IFIT5, IFIH1 (MDA5), MX1, RSAD2 (viperin), CMPK2, SOCS1, and SCNN1D." (PMID 38675946, 2024). "Expression of eight of these genes (IFIH1, OAS2, IFIT1, IFIT2, IFIT3, IFIT5, USP18 and DDX58F) was significantly elevated in response to VSV-ΔM51 infection in permissive cells, but not in resistant PDACs." (PMID 27533247, 2016).
cancer (15 papers, 2015 to 2025). A tumor composed of atypical neoplastic, often pleomorphic cells that invade other tissues. "Recently, human IFIT5 has been implicated in cancer progression." (PMID 31921891, 2019). "IFIT5, similar to other IFITs, and depending on cancer types, elicits either pro-oncogenic or tumor suppressive functions depending on cancer types and can serve as either an unfavorable or favorable clinical marker." (PMID 40564154, 2025). "In this cancer, IFIT5 protein has been shown to induce EMT and promote cell migration/invasion via micro-RNA regulatory mechanisms and was proposed to act as an oncogene." (PMID 40564154, 2025). "Elevated levels of IFIT1, IFIT3 and IFIT5 have been shown to play significant roles in cancer progression, while the decreased expression of IFIT2 has been reported to enhance invasion, tumor progression, and drug resistance in various cancer types." (PMID 36979874, 2023). "We found that the expression of IFIT5 mRNA was higher in high-grade BCa tissues or NMIBC tissues with carcinoma in situ (CIS)." (PMID 31164632, 2019). "The second network contained 6 of the identified autoantigens (AGO1, CSNK1G1, IFIT5, PHC3, SRP19, and UBE2S) out of the 35 molecules associated with cancer, organismal injury and abnormalities." (PMID 31494269, 2019). "In conclusion, this study is the first report to demonstrate the oncogenic role of IFIT5 in BCa to facilitate EMT leading to cancer invasiveness and its clinical relevance with poor survival of BCa patient." (PMID 31164632, 2019). "In addition to its pro-oncogenic role, IFIT5 also appears to act as a tumor suppressor in other cancers." (PMID 40564154, 2025). "Additionally, IFIT5 may affect the course of cancer and the epithelial-mesenchymal transition." (PMID 40658715, 2025). "Although more work is required to accurately elucidate the impact of IFIT proteins in cancer, recent investigations reveal that IFIT1, IFIT3, and IFIT5 promote metastasis, while IFIT2 acts against neoplastic cells by promoting apoptosis." (PMID 36851555, 2023). "Among 33 types of human cancers, IFIT1, IFIT2, IFIT3, IFIT5 were abnormally expressed in 21, 23, 24 and 23 cancer types respectively." (PMID 37980495, 2023). "However, the expression of IFIT5 and NCK1 were positively correlated with the immune score in most cancers." (PMID 36226166, 2022). "However, the expression of CYFIP2, IFIT5, and NUDT4 were negatively correlated with the prognosis of most cancer patients." (PMID 36226166, 2022). "No data of IFIT5 involvement in cancer has been reported so far." (PMID 29844869, 2018).
tumor (12 papers, 2019 to 2025). "Consistent with in vitro observation, the incidence of DU145 tumorigenesis is significantly reduced by IFIT5 loss, which is similar with their tumour size and weight." (PMID 35908276, 2022). "Apparently, elevated IFIT5 is able to increase in vivo tumor growth as well as EMT associated with in vitro cell migration and invasiveness." (PMID 31164632, 2019). "In bladder cancer, expression of IFIT5 has been reported to be negatively correlated with favorable pathological characteristics of the tumor and patient survival." (PMID 40564154, 2025). "Consistently, knocking down IFIT5 in t‐CRPC cell can significantly reduce in vitro prostasphere formation as well as decrease in vivo tumour initiating capability." (PMID 35908276, 2022). "Taken together, we conclude that IFIT5 represents a new oncogene in BCa with unique mechanism of action in modulating tumor suppressor miR." (PMID 31164632, 2019). "We further delineate the mechanism of action of IFIT5 to modulate tumor suppressor miR-99a in BCa." (PMID 31164632, 2019). "Two weeks after injection, the tumor volume of IFIT5-OE 5637 xenografts was significantly higher than the controls, in contrast, the tumor volume of IFIT5-KD UM-UC-3 xenografts was significantly smaller than the controls, indicating that IFIT5 could promote BCa development." (PMID 31164632, 2019). "Only EIF4E3, IFIT5, EIF4G3, NUDT16, NUDT10, NCBP3, and NUDT11 showed decreased expression in tumor tissues." (PMID 41406096, 2025). "Genes such as EIF4E3, IFIT5, EIF4G3, NUDT16, NUDT10, NCBP3, and NUDT11 showed lower expression in tumor tissues, whereas other genes were highly expressed." (PMID 41406096, 2025). "In contrast, tumor suppressive properties have been suggested in a recent study in AML, that showed that upregulation of IFIT5 can take place via regulation by histone demethylase PHF8, triggering a differentiation-apoptosis network and counteracting the growth of AML cells." (PMID 40564154, 2025). "The increased transcripts for EGR1, interferon-induced proteins (IFI6, IFIT1, IFIT3, IFIT5), and MHC class II (HLA-DRA) indicated strong stimulation of IFN signaling, which could result in activation of macrophages in the tumor microenvironment." (PMID 37834191, 2023). "However, there were a few downregulated genes in tumor samples, such as CYFIP1, IFIT5, DCP2, and EIF4E3." (PMID 36761423, 2022). "Four genes (MRPL54, ZC3H13, IFIT5, and PPARGC1A) were downregulated and may function as tumor suppressor genes in HCC, and showed a positive correlation with prognosis." (PMID 33251144, 2020).
cardiovascular disease (2 papers, 2021 to 2023). "Previous studies have demonstrated that IFIT1, IFIT3 and IFIT5 play an important regulatory role in cardiovascular disease." (PMID 34753383, 2021). "For example, IFIT5 is one of the candidate genes for cardiovascular disease." (PMID 37684436, 2023).
IFIT5 also shares sentences with these, for which no sentence is quoted: bacterial infection (1 paper); bovine respiratory disease complex (1); bronchitis (1); co-infection (1); H1N1 virus infection (1); heart failure (1); liver fibrosis (1); lung carcinoma (1); myeloid leukemia (1); neurological disorder (1); pneumonia (1); primary immunodeficiency (1); respiratory syncytial virus infections (1); viral diseases (1).